MC4R (melanocortin 4 receptor)
Diseases named in the same sentence as MC4R in open-access papers (continued):
Sharing a sentence is not in itself a finding about the gene and the disease.
Obesity (continued). "The present study supported our previous findings and suggests that liraglutide exerts the suppressive effects on hyperphagia, obesity, and hyperglycemia induced by the perturbed central MC4R signaling." (PMID 24804243, 2014). "For example, the well-known obesity-related FTO gene interacts with APOE which in turn, is associated with Alzheimer's disease and with MC4R, resulting in a higher chance of breast cancer." (PMID 25071839, 2014). "Hardy and colleagues took variants from the two most commonly reported obesity genes, FTO and MC4R, to see if they were associated with life course body size." (PMID 23349760, 2013). "Mice with targeted disruption of the MC4R have been shown to develop late-onset obesity with hyperphagia, hyperinsulinemia, and hyperglycaemia." (PMID 23739675, 2013). "In mice and humans, decreased melanocortin 4 receptor (MC4R) activity increases feeding and obesity." (PMID 23613935, 2013). "As it is thought that Avy/a obesity is driven to a large degree by Mc4r antagonism, it is plausible that Mc4r antagonism also plays a role in increased nicotine sensitivity." (PMID 24289264, 2013). "Eight variants representing 8 early-life obesity-susceptibility loci, including FTO and MC4R, were genotyped in 2215 boys and 2449 girls aged 16 years from the population-based Northern Finland Birth Cohort 1986." (PMID 24040077, 2013). "Genetic defects that interrupt MC4R signaling in humans result in lower blood pressure despite prevailing obesity." (PMID 24400148, 2013). "On the other hand, MC4R and BDNF mutations are known to cause monogenic obesity, and common variation in these genes has also been previously associated with severe obesity." (PMID 23950976, 2013). "Most Agouti viable yellow (Avy) mice display constitutive expression of agouti protein, which acts as an inverse agonist at the melanocortin receptor 4 (Mc4r), resulting in adult-onset obesity as well as an altered sensitivity to some drugs of abuse." (PMID 24289264, 2013). "A meta-analysis of associations between BMI and approximately 2.4 million SNPs in 27,715 East Asian subjects with replication studies in 37,691 and 17,642 additional East Asian subjects confirmed that loci at MC4R and BDNF were associated with obesity." (PMID 23431394, 2013). "We have recently reported that melanocortin-4 receptor (MC4R) deficient (MC4R-KO) mice on a high-fat diet (HFD) exhibit a liver condition similar to human NASH, which is associated with obesity, insulin resistance, and dyslipidemia." (PMID 24349208, 2013). "MC4R alone are clearly important for glucose homeostasis as demonstrated by the fact that MC4R knockout mice are hyperinsulinemic prior to the onset of obesity and have hepatic and peripheral insulin resistance." (PMID 23550218, 2013). "In contrast, previous work examining sympathetic activation in obese db/db mice indicated an increase in renal sympathetic nerve activity (RNSA) with leptin-deficient obesity, but a dissociation of obesity and RNSA in MC4R KO mice." (PMID 24400148, 2013). "Despite obesity and significant metabolic dysfunction, blood pressure was similar in WT and MC4R KO rats from young adulthood to full maturity (10 through 18 weeks)." (PMID 24400148, 2013). "Common variations at the loci harboring the fat mass and obesity gene (FTO), MC4R, and TMEM18 are consistently reported as being associated with obesity and body mass index (BMI) especially in adult population." (PMID 24348519, 2013). "Although the association between both MC4R and NEGR1 and risk of obesity has been confirmed in a plethora of studies and populations, the ENPP1 association signal with obesity is more controversial." (PMID 23375129, 2013). "Taken together, these data suggest that the MC4R rat is a model of obesity and insulin resistance in the prediabetic state." (PMID 24400148, 2013).
Obesity (continued). "First, it provides confirmation of the essential cardiovascular feature of MC4R deletion is a new model – dissociation of obesity and hypertension in the rat." (PMID 24400148, 2013). "The purpose of our study was to determine the effects of genetic obesity on angiogenic balance, endothelial function, and blood pressure in pregnant MC4R+/− and MC4R+/+ rats." (PMID 24159378, 2013). "Second, it provides new insights into how sympathetic control of cardiovascular system is modulated in obesity and the role, or lack thereof, of MC4R in vascular sympathoactivation." (PMID 24400148, 2013). "In humans, mutations in melanocortin receptor 4 (MC4R) are the most common genetic cause of monogenic, or single-gene, obesity." (PMID 24046387, 2013). "We then used the MC4R+/− rat to examine the effects of obesity on angiogenic factors, vasorelaxation, and blood pressure phenotypes in pregnancy." (PMID 24159378, 2013). "The metabolic phenotype of the MC4R KO rat was consistent with obesity-related insulin resistance, including elevations in plasma levels of cholesterol, triglycerides, free fatty acids, HbA1c, and insulin." (PMID 24400148, 2013). "The high penetrance differentiates CNV-associated obesity from SNP associated obesity in which, except for some very rare mutations in a few genes of the leptin/melanocortin pathway (LEP, MC4R, etc.), almost all variants have low penetrance." (PMID 22654670, 2012). "In contrast, two SNPs of the MC4R gene: I251L and V103L have been shown to be negatively correlated with obesity." (PMID 23185251, 2012). "This posed the question as to whether obesity-linked receptor variants differ in the main mechanism by which they are retained in the ER, with MC4R I316S having more propensity to misfold and then to be ubiquitinated and with MC4R P272L being ubiquitinated in the face of correct folding." (PMID 23251400, 2012). "Melanocortin-4 Receptor (MC4R) mutations, the most frequent known cause of monogenic obesity, affect the regulation of energy homeostasis." (PMID 23185251, 2012). "Loss of function mutations of the MC-4R, the most important melanocortin receptor (MCR), is the most common genetic etiology of obesity and accounts for 3–5% of severe human obesity, highlighting the relevance of this pathway in humans." (PMID 22518191, 2012). "The relationship between obesity and the TE type by the risk alleles of FTO and MC4R was consistent with the findings of a previous report, which indicated that TE subjects tend to have higher fat masses." (PMID 19822564, 2011). "Actually, obesity is a complex trait, and many genes are related to obesity, such as MC4R, MAF, and NPC1." (PMID 21651756, 2011). "When the population was stratified by SCM type (excluding subjects with the rare TY type; 0.6% of our study population), we observed different relationships of FTO and MC4R with obesity-related phenotypes." (PMID 19822564, 2011). "To examine the relation between the obesity-associated FTO rs9939609 and MC4R rs17782313 and endometrial cancer risk, we utilized pooled data within the Epidemiology of Endometrial Cancer Consortium (E2C2)." (PMID 21347432, 2011). "The most recent GWAS has confirmed that the FTO gene, in addition to two other obesity susceptibility genes (MC4R and NPC1, reviewed below) are associated with childhood and adult obesity within a European population." (PMID 22043166, 2011). "A few smaller GWAs focused on other forms of obesity (early onset, extreme obesity and/or morbid adult obesity) and replicated FTO, MC4R and TMEM18 BMI-associations." (PMID 21466928, 2011). "The first definitive study demonstrating that the MC4R gene has a role in promoting obesity was performed by targeted disruption of this gene (Mc4r) within mice; this explained excessive weight gain in what was commonly referred to as the agouti mouse model." (PMID 22043166, 2011).
Obesity (continued). "At the end of the first obesity GWAS wave, SNPs near the MC4R gene were identified, both in an independent GWAS and through meta-analysis of several GWAS." (PMID 21912638, 2011). "Common variants of fat mass and obesity associated (FTO) and melanocortin 4 receptor (MC4R) genes have been associated with increased body mass index (BMI) by affecting energy intake." (PMID 19822564, 2011). "Consistent with previous studies, we replicated the association of MC4R with BMI in a Korean population for the first time and we also confirmed the association of the FTO LD block with obesity-related phenotypes in Koreans." (PMID 19822564, 2011). "Nineteen loci have been identified and five of them only are associated with BMI / obesity (FTO, MC4R,NRXN3, TFAP2B, MSRA)." (PMID 22043164, 2011). "Recessive forms of obesity caused by homozygous / heterozygous compound loss of function mutations in five genes (LEP, LEPR, POMC, PCSK1 and MC4R) have been reported to date." (PMID 22043164, 2011). "The melanocortin 4-receptor (MC4R) gene is responsible for the most common forms of childhood and adult obesity." (PMID 22043166, 2011). "For obesity variants, we selected 7 FTO SNPs (rs1421085, rs1121980, rs8057044, rs8050136, rs9939609, rs9941349 and rs9930506) and 2 MC4R SNPs (rs17782313 and rs12970134)." (PMID 21573225, 2011). "The obesity-risk-allele score based on genotypes at eight SNPs associated with childhood BMI (in/near to: FTO, MC4R, TMEM18, GNPDA2, NEGR, KCTD15, BDNF, and ETV5) ranged from 2 to 15 alleles." (PMID 20520848, 2010). "Targeted genetic manipulation in mice has also established vital regulatory roles of molecules in obesity such as the melanocortin 4 receptor (MC4R)." (PMID 20860848, 2010). "We searched for over-transmission of ‘obesity haplotypes’ to determine if the distant non-coding 3′ SNPs (rs17782313 and rs12970134) belong to haplotypes which extend into the MC4R locus." (PMID 21085626, 2010). "Several companies have MC4R agonists that are being investigated in the treatment of obesity, including piperazinebenzylamines, piperazinethylamines, piperazinesulfonamides and other small-molecule agonists." (PMID 27713245, 2010). "A meta-analysis supported the evidence of the obesity-protective effect of MC4R Leu251 (odds ratio = 0.52)." (PMID 21085626, 2010). "We also re-identified variants in or near FTO, MC4R, and TMEM18 to be associated with extreme obesity." (PMID 20421936, 2010). "The melanocortin-4-receptor (MC4-R) is a potentially important drug target for the treatment of obesity." (PMID 20877250, 2010). "We observed that genetic variants in or near FTO, MC4R, TMEM18, SDCCAG8, and TNKS/MSRA were robustly associated with early-onset obesity." (PMID 20421936, 2010). "The newest study identifying 6 additional obesity predisposing variants in combination with FTO and MC4R explained only 0.84% of the variance in BMI." (PMID 20532202, 2010). "We analyzed a genomic region (364.9 kb) encompassing the MC4R in GWAS data of 424 obesity trios (extremely obese child/adolescent and both parents)." (PMID 21085626, 2010). "In humans, fat mass, and genetic markers for obesity genes MC4R and FTO, are strongly related to bone mineral content, total body and regional, measured by DXA." (PMID 19878575, 2009). "The variable penetrance and expressivity of obesity in heterozygous individuals argues that the MC4R acts in concert with a number of other genes to regulate energy storage under presumed conditions of a sedentary lifestyle and high-fat diet." (PMID 19284607, 2009). "Recent studies have identified two strong obesity candidate genes, the fat mass and obesity associated (FTO) and melanocortin 4 receptor (MC4R) –18." (PMID 19390624, 2009). "Insulin, which is increased in MC4R-/- mice with late-onset obesity, belongs to the factors that augment LH sensitivity of interstitial gland cells." (PMID 19309531, 2009).
Obesity (continued). "This indicates that reduced fertility due to erectile dysfunction in male MC4R-/- mice is secondary to obesity." (PMID 19309531, 2009). "We focused on physical activity as an environmental risk factor, and on the GWA identified obesity variants in FTO (rs9939609) and near MC4R (rs17782313) as genetic risk factors." (PMID 18682847, 2008). "Several monogenic obesity genes have been cloned in mice including leptin, leptin receptor, carboxypeptidase, melanocortin-4 receptor, and the orexigenic agouti protein." (PMID 18752667, 2008). "This distinguishes the Snord116del mouse model from the genetic mouse models of obesity, including ob/ob, db/db, Sim1 haploinsufficiency, Mc4r deletion and others that lack proper homeostasis control." (PMID 18320030, 2008). "The evidence, either genetic or neuropharmacological, for the key role of MC4R in feeding and the pathogenesis of obesity is as follows." (PMID 17764572, 2007). "THIQ was synthesized as a peptidomimetic of the potent α-MSH analog MT-II as a potential treatment for obesity and is approximately 30-fold more potent at MC4R than α-MSH." (PMID 17668051, 2007). "Next, the role of MC4R in the regulation of body weight has generated the interest of pharmaceutical companies that have created potent small-molecule agonists of MC4R to treat obesity and can be used to activate an MC4R-based RASSL." (PMID 17668051, 2007). "Moreover, the efficacy of these drugs in MC4R KO mice aligns with clinical studies, indicating that MC4R KO mice serve as a reliable animal model for obesity research." (PMID 41723268, 2026). "Our data demonstrate that setmelanotide reactivates PVN MC4R signaling, suppresses appetite, and reverses metabolic pathology in HO, providing mechanistic insight and highlighting the urgent need for innovative therapies for CNS-related obesity." (PMID 41601974, 2026). "The melanocortin-4 receptor (MC4R) is highly expressed in the hypothalamus, and mutations in this gene are closely associated with the development of hereditary obesity and early-onset severe obesity in humans." (PMID 41615915, 2026). "In particular there is a high burden of metabolic disturbances, such as obesity, hyperphagia, and type 2 diabetes, due to the impaired leptin-melanocortin-4 receptor (MC4R) pathway that prevents appropriate activation of MC4R that is normally responsible for signaling hunger and satiety." (PMID 41048439, 2025). "Thus, early genetic studies of severe obesity (SevO) focused on identifying gene-disrupting mutations in the leptin-melanocortin pathway (e.g., LEPR, MC4R, POMC), which are linked to early-onset SevO through dysregulation of food intake and food preferences." (PMID 40939575, 2025). "One concern is that Set is used for weight loss only in patients with mutations in the POMC/leptin/MC4R pathways, but not in the most common polygenic form of obesity." (PMID 40232848, 2025). "In our study of patients with monogenic obesity, MC4R emerged as the most commonly affected gene." (PMID 40523925, 2025). "Similarly to MC4R, human genetic variants in MRAP2 have been identified in several families and individuals with obesity that reduce MC4R activity." (PMID 41401256, 2025). "In this study, we investigated the contribution of MC4R signaling versus obesity per se in the etiology of the reproductive impairments observed in Mc4r null mice, which could explain similar impairments observed in humans." (PMID 40674128, 2025). "The intrafamilial phenotypic variability seen among heterozygous carriers is consistent with previous findings that MC4R-associated obesity does not manifest uniformly in all individuals with a pathogenic variant." (PMID 40428329, 2025). "While setmelanotide, a melanocortin-4 receptor agonist, may be an effective therapy for obesity in these conditions (especially BBS), its cost limits accessibility for many patients." (PMID 41312179, 2025).
Obesity (continued). "In monogenic obesity, there is a generally clear link between genetic variants and biological functions, particularly for genes in the leptin and melanocortin signaling pathways (LEPR, MC4R, and POMC)." (PMID 38849463, 2025). "Similarly to the binding of α-MSH to MC4R, γ-MSH binds to MC3R to regulate appetite and energy expenditure, and a loss of function of both receptors leads to severe early-onset obesity." (PMID 40001512, 2025). "Genetic factors such as FTO, MC4R, and LEPR polymorphisms may further influence susceptibility to obesity." (PMID 41228239, 2025). "Moreover, genetic studies further emphasize the heterogeneity of obesity, with variants in POMC and MC4R contributing to severe early-onset forms." (PMID 41333852, 2025). "This study aimed to investigate the gastric expression of FTO and MC4R genes and their association with circulating levels of leptin, adiponectin, and ghrelin in individuals with and without obesity." (PMID 41423640, 2025). "Important genes associated with monogenic obesity consist of leptin (LEP), leptin receptor (LEPR), proopiomelanocortin (POMC), prohormone convertase 1 (PCSK1), MC4R, single-minded homolog 1 (SIM1), brain-derived neurotrophic factor (BDNF), and its receptor NTRK2 (commonly referred to as TrkB)." (PMID 40428329, 2025). "Human mutations in MC4R and MRAP2 are associated with obesity." (PMID 41401256, 2025). "Unlike causal genes for monogenic obesity, such as MC4R or LEP, which have a direct role in early-onset and severe forms of obesity, FTO influences susceptibility through regulatory mechanisms." (PMID 40806129, 2025). "In summary, this study’s results add to the expanding knowledge on MC4R-related obesity and highlight the need to combine clinical, genetic, and molecular information to enhance understanding of the pathogenicity and clinical effects of rare variants such as MC4R:c.216C>G." (PMID 40428329, 2025). "Specifically, homozygous loss-of-function (LoF) mutations in genes such as LEP, LEPR, and homozygous and heterozygous in MC4R result in uncontrollable hyperphagia, an eating disorder characterized by excessive hunger and food intake, leading to extreme early-onset obesity." (PMID 39237720, 2025). "Owing to a chronic imbalance between energy intake and expenditure, hyperphagia may contribute to development of severe obesity in individuals with rare MC4R pathway diseases." (PMID 40560452, 2025). "This occurrence was higher than for the well-established obesity target melanocortin 4 receptor." (PMID 40133016, 2025). "However, biases related to genetic predispositions must be considered, as genes such as FTO, MC4R, PPARG, and TMEM18 are associated with obesity and metabolic disorders, especially in European populations." (PMID 40827223, 2025). "While its role in syndromic obesity is established, emerging evidence suggests that MC4R agonism may extend beyond energy homeostasis to modulation of immune responses and inflammation." (PMID 41333852, 2025). "Notably, certain genes such as MC4R, BDNF, and PCSK1 are implicated in both monogenic and polygenic obesity, depending on the type and frequency of the variant." (PMID 40281302, 2025). "We use this analogy to suggest that the high frequency of mutations observed in GPR61, and even the higher cumulative number of mutations than for MC4R, may indicate the role of GPR61 in metabolism/obesity." (PMID 40133016, 2025). "This study investigated the association between gastric expression of FTO and MC4R genes and circulating levels of leptin, adiponectin, and ghrelin in individuals with and without obesity." (PMID 41423640, 2025). "Notably, rare, pathogenic mutations in all the genes involved in leptin driven melanocortin pathway (LEP, LEPR, POMC, PCSK1, MC4R, primarily) lead to severe early-onset obesity accompanied by eating disorders." (PMID 39237720, 2025).